ID4 (inhibitor of DNA binding 4)
Diseases named in the same sentence as ID4 in open-access papers (continued):
Sharing a sentence is not in itself a finding about the gene and the disease.
prostate carcinoma (continued). "In this report, we demonstrate that Id4 expression is attenuated in prostate cancer due to promoter hypermethylation." (PMID 23342267, 2012). "Id4 expression was also down-regulated in prostate cancer line DU145 due to promoter hyper-methylation." (PMID 19500415, 2009). "Id4 appears to be androgen regulated in normal prostate epithelial cells and in the androgen sensitive prostate cancer cell line LNCaP." (PMID 19500415, 2009). "Ectopic Id4 expression in DU145 prostate cancer cell line led to increased apoptosis and decreased cell proliferation due in part by an S-phase arrest." (PMID 19500415, 2009). "The molecular basis of Id4 down-regulation and its significance in prostate cancer was studied in a well characterized prostate cancer cell line DU145." (PMID 19500415, 2009). "Our data, however does confirm that Id4 is involved in blocking the cell cycle of prostate cancer cell lines DU145 and PC3." (PMID 19500415, 2009). "On the contrary, our analysis of five independent prostate cancer microarray databases strongly suggests that Id4 is down-regulated in prostate cancer." (PMID 19500415, 2009). "In contrast, the normal human prostate epithelial cells (PrEC) and prostate cancer cell lines (LNCaP) express Id4." (PMID 19500415, 2009). "Consolidated data from all these studies demonstrated that Id4 is significantly (T-values > 5 and low P-values < E-6) down-regulated in prostate cancer samples." (PMID 19500415, 2009). "PC3 cells are weakly positive for Id4 expression but nevertheless provide a good model to investigate the effect of ectopic Id4 expression on prostate cancer cells." (PMID 19500415, 2009). "Data mining of published microarray databases was used to determine the relative expression levels of Id4 in clinically relevant cases of prostate cancer as compared to controls and benign prostate hyperplasia." (PMID 19500415, 2009). "It is necessary to analyze Id4 methylation status and expression levels in primary tumor samples as well as in normal prostate tissues in order to further clarify the role of epigenetic silencing of Id4 in prostate cancer." (PMID 19500415, 2009). "Id4 expression is also significantly reduced in prostate cancer samples as determined through data mining." (PMID 19500415, 2009). "Id4 expression is undetectable or weakly expressed in androgen independent DU145 cells whereas its expression is observed (low) in PC3 prostate cancer cell lines." (PMID 19500415, 2009). "For example, ID4 gene is typically highly expressed in normal prostate tissue but exhibits decreased expression in prostate cancer tissue and gradually decreases with cancer progression, highlighting the conventional inactivation pattern of a tumor-suppressor gene." (PMID 38443680, 2024). "In addition, ID4 acts as a tumor suppressor in prostate cancer, while serves as a proto-oncogene in bladder cancer." (PMID 35574406, 2022). "Thus, the role of ID4 in prostate development and as a prostate cancer tumor suppressor is well established." (PMID 33884281, 2021). "Previous studies have shown that Id4 expression is dysregulated in some human cancers, and Id4 may act as a tumor suppressor to inhibit cell proliferation and increase cell apoptosis in prostate cancer." (PMID 33936204, 2021). "However, in the prostate cancer, Id4 acted as a tumor suppressor, and Id4 overexpression in the PC3 cells (one of the highly malignant prostate cancer cell lines) increased apoptosis and inhibited cell proliferation and migration." (PMID 33936204, 2021). "The data of this study, showing that Id4 may act to impede the evolution of lung cancer metastasis, are similar to those from prostate cancer, glioblastoma, and thyroid tumors." (PMID 31847356, 2019). "Recent studies have also demonstrated the function of Id4 in breast and prostate cancers." (PMID 28143562, 2017). "Indeed, Id4 expression is epigenetically silenced in prostate cancer, whereas its ectopic expression suppresses the cancer phenotype." (PMID 28122577, 2017).
prostate carcinoma (continued). "In prostate cancer, Id4 was down-regulated because of promoter hypermethylation, which provided evidence that Id4 may be a tumor suppressor." (PMID 28143562, 2017). "However, it has been also reported that primary prostate cancers display high levels of Id4, which has been suggested to favor distant metastasis." (PMID 28122577, 2017). "Collective observations based on our studies led us to hypothesize that ID4 could be involved in selectively regulating AR activity through FKBP52 in prostate cancer." (PMID 28252832, 2017). "Similarly, ectopic ID4 expression led to increased apoptosis and decreased cell proliferation due in part by an S‐phase arrest in prostate cancer." (PMID 28452111, 2017). "Similar to our findings, cytoplasmic ID4 staining has been observed in prostate cancer cells." (PMID 25642713, 2015). "Whether the EZH2-DNMT mechanism is specific to prostate cancer or a more general pro-cancer pathway involved in ID4 gene silencing remains to be investigated." (PMID 25115397, 2014). "Thus increased EZH2 expression and its subsequent recruitment appears to be the primary mechanism involved in epigenetic silencing of ID4 in prostate cancer." (PMID 25115397, 2014). "In contrast, ID4 promoter was highly enriched for the RNA polymerase II and H3 acetylation (0.55+0.078 and 0.70+0.144, P<0.001, respectively) in benign prostate as compared to prostate cancer (0.12+0.061 and 0.35+0.051, respectively)." (PMID 25115397, 2014). "The EZH2-DNMT dependent mechanism at least in prostate cancer suggest that targeting this pathway through specific inhibitors resulting in general epigenetic re-programming including up-regulation of ID4 could be a strong therapeutic strategy." (PMID 25115397, 2014). "The data presented here supports an EZH2 dependent epigenetic silencing of ID4 in prostate cancer." (PMID 25115397, 2014). "Increased EZH2 but decreased ID4 expression in prostate cancer strongly supports this model." (PMID 25115397, 2014). "Collective observations led us to hypothesize that increased EZH2 expression could be involved in down-regulation of ID4 in prostate cancer." (PMID 25115397, 2014). "Id4 expression in the prostate thus appears in contrast with the expression of other Id genes (Id1 and Id3) which are expressed at low to negligible levels in the normal prostate although their expression increases significantly in prostate cancer." (PMID 23786676, 2013). "Finally, prostate cancer cell line models in which Id4 was either silenced or over-expressed confirmed that Id4 regulates NKX3.1, Sox9 and PTEN." (PMID 23786676, 2013). "In particular, Id4 could support the function of the AR as a suppressor of epithelial proliferation in the mature prostate, which is defective in prostate cancer." (PMID 23786676, 2013). "A direct relationship between Id4 promoter methylation with Id4 expression by qRT-PCR was investigated in a subset of prostate cancer (n = 10 each for completely methylated and n = 7 for partially methylated prostate cancer samples) and benign prostate samples (n = 9)." (PMID 23342267, 2012). "Id4 immuno-histochemistry was performed on normal/benign prostate (n = 20, disease free) and prostate cancer (n = 54: stage I–III) tissue microarrays to determine their association with prostate cancer." (PMID 23342267, 2012). "We used prostate cancer tissue microarrays to investigate Id4 expression." (PMID 23342267, 2012).
prostate carcinoma (continued). "We next investigated the expression of Id4 in prostate cancer tissue." (PMID 23342267, 2012). "A previous study reported increased Id4 expression with increasing grade of prostate cancer." (PMID 23342267, 2012). "Data mining was used to demonstrate Id4 expression in prostate cancer." (PMID 19500415, 2009). "A developmental block due to loss of Id4 may represent a threshold which need to be overcome for the development of prostate cancer even in the absence of major tumor suppressor Nkx3.1 and Pten and over-expression of myc." (PMID 33884281, 2021). "Thus PRMT5 localization (predominantly cytoplasmic) in prostate cancer does not correspond with its role in ID4 methylation or association with CpG islands, which as one would expect to be in the nucleus." (PMID 25115397, 2014). "However, in spite of these complex alterations, we did not observe a significantly greater number of pre-neoplastic lesions in Id4-/- prostate suggesting the possibility of mechanisms/pathways that restrains the formation of significant pre-cancerous lesions and prostate cancer." (PMID 23786676, 2013). "In prostate cancer samples, Id4 expression was clearly dependent on Id4 promoter hypermethylation: Id4 expression significantly decreased by 76 and 222-fold (essentially un-detectable) in partially methylated and completely methylated prostate cancer samples, respectively." (PMID 23342267, 2012). "Thus, decreased Id4 expression in prostate cancer is observed at both transcript and protein level." (PMID 23342267, 2012). "There were 24 genes that had been reported correlating with prostate cancer, among which TGFB3, PTN, ID4 were widely studied." (PMID 29190897, 2017). "Inhibitor of differentiation 4(ID4), a helix loop helix transcriptional regulator has emerged as a major tumor suppressor in prostate cancer (PCa)." (PMID 27487149, 2016). "Id4 expression was primarily nuclear and was occasionally observed in stage I (red arrows) but rarely observed in stage II and III prostate cancers." (PMID 23342267, 2012). "ID4 has been found to be epigenetically dysregulated in various cancer types: leukemia, AML, CLL, ALL, glial neoplasia, gastric cancer, pancreatic cancer, colorectal, lymphoma, cholangiocarcinoma, esophageal, lung and prostate cancers." (PMID 33133131, 2020). "In addition to these ID4 protein partners, the current approach also identified FKBP52 as a potential ID4 binding partner in prostate cancer LNCaP cells." (PMID 28252832, 2017). "Id4 also restores androgen receptor expression and activity in the androgen receptor negative prostate cancer cell line DU145." (PMID 23786676, 2013). "The DU145 prostate cancer cell line is negative or expresses very low Id4 and hence is an excellent model to study mechanisms involved in its down-regulation." (PMID 19500415, 2009). "Given that ID4 is undetectable or weakly expressed in prostate cancer DU145 cells, they provide an ID4‐negative background as compared to the LNCaP cells wherein ID4 is endogenously expressed, further confirming the domain‐specific interaction between ID4, FKBP52, and AR–protein complexes." (PMID 28252832, 2017). "Proteomic analysis between prostate cancer cell line LNCaP (L+ns) and LNCaP lacking ID4 (L(−)ID4) revealed elevated levels of Hsp27 and FKBP52, suggesting a role for these AR‐associated co‐chaperones in promoting constitutively active AR signaling in L(−)ID4 cells." (PMID 28252832, 2017). "However direct evidence demonstrating the ID4 gene expression is independent of PRMT5 in prostate cancer remains to be investigated." (PMID 25115397, 2014). "Furthermore, Id4 expression progressively decreased in prostate cancer cell line LNCaP and with no expression in androgen-insensitive LNCaP-C81 cell line." (PMID 23342267, 2012).
prostate carcinoma (continued). "The effect of Id4 leading to decreased proliferation and S-phase arrest in DU145 prostate cancer cell line may be due to increase in the expression of tumor suppressors E-cadherin, p27, p21 and the bHLH transcription factors E12/E47 and/or activation of previously silenced tumor suppressors." (PMID 19500415, 2009). "ID4 expressing (LNCaP) and non-expressing (DU145 and C81) prostate cancer cell lines were used to investigate EZH2, H3K27me3 and DNMT1 enrichment on ID4 promoter by Chromatin immuno-precipitation (ChIP)." (PMID 25115397, 2014). "This hypothesis was examined in the present study by over-expressing Id4 in androgen receptor negative DU145 and PC3 prostate cancer cells." (PMID 19500415, 2009).
glioblastoma (15 papers, 2005 to 2024). The most malignant astrocytic tumor (WHO grade IV). "In stark contrast to Id1–3, Id4 correlates with survival of glioblastoma patients by decreasing MMP2 expression, a secreted proteinase key for brain tumor invasion, via a direct inhibitory interaction with the bHLH TF Twist1." (PMID 34302526, 2022). "It was found that Id4 increases platelet-derived growth factor (PDGF) and nitric oxide synthase 2 (NOS2) expression levels in glioblastoma cells; this positive regulatory circuit of PDGF-NO-Id4 enhances the self-renewal of glioblastoma cells." (PMID 32708313, 2020). "Using tissue microarrays and immunohistochemistry, the differential expression of Id4 was found in various grades of astrocytomas, suggesting the possible transformation of low- to high-grade astrocytoma (i.e., glioblastoma)." (PMID 32708313, 2020). "Recently, scientists also found that Id4 is involved in the suppression of matrix metalloproteinase 2 (MMP2)-mediated cell invasion in glioblastoma and also in the modulation of miR-342-regulated breast cancer type 1 susceptibility protein (BRCA1) expression." (PMID 31847356, 2019). "Particularly, ID4 can act as a tumor suppressor and as an oncogene in different tumor types, e.g., prostate, gastric, glioblastomas, and colorectal tumors." (PMID 30139383, 2018). "Id2 and Id4 play a crucial role in regulating the glioblastoma multiforme (GBM) stem-like cells differentiation, thus reducing their cancer initiating potential." (PMID 28122577, 2017). "Id4 mRNA levels were found to have increased in human glioblastoma multiforme (GBM) when compared to normal brain tissue." (PMID 21293053, 2010). "Id4 is involved in suppressing the MMP2-mediated cell invasion in glioblastoma." (PMID 33936204, 2021). "Id4 was also found to possess proangiogenic function in the growth of glioblastoma." (PMID 32708313, 2020). "In cancer, ID4 presents again divergent roles since it has been described to act as a tumor suppressor in prostate, lung, and gastric tumors, and as an oncogene in ovarian cancer and glioblastomas." (PMID 30139383, 2018). "ID4 protein overexpression has been observed in triple negative breast cancer and glioblastoma." (PMID 25642713, 2015). "Some genes that were topmost DE in glioblastoma nuclei include RMST, ID4 and PBX3." (PMID 36865335, 2023). "Further in silico analysis of TIMER2 glioblastoma patient data sets also suggested that RCN3 showed a positive correlation with stemness marker CD44 and a negative correlation with differentiation markers such as ID4, MAP2, and NTRK5." (PMID 37046668, 2023).
glioma (15 papers, 2005 to 2023). A benign or malignant brain and spinal cord tumor that arises from glial cells (astrocytes, oligodendrocytes, ependymal cells). "ID4 is a reprogramming factor that differentiates glioma cells and immortalized astrocytes to glioma CSCs." (PMID 36661515, 2023). "Jeon reported that ID4 drive drug resistance of glioma cells by miR-9-SOX2-ABCC3/ABCC6 regulatory pathway." (PMID 32328189, 2020). "The over-expression of ID4 in glioma stem cells directly inhibited the expression of microRNA-9 by inhibiting the expression of SOX2, which in turn regulated ATP-binding cassette (ABC) transporters, finally leading to less sensitivity to nitrosourea drugs in cancer cells." (PMID 32328189, 2020). "Several studies showed the potential roles of Id4 in glioma." (PMID 32708313, 2020). "Besides notch activity, PDGF- nitric oxide synthase (NOS)-inhibitor of differentiation 4 (ID4)-miR129 axis are additional mediators involved in glioma progression." (PMID 32264958, 2020). "Interestingly, Inhibitor of Differentiation 4 (ID4) induces de-differentiation of human glioma cells towards a GSC phenotype and enhances SOX2 expression by suppressing miR-9*." (PMID 31450858, 2019). "However, both of these ABC transporters are transcriptionally regulated by SOX2, which is elevated in glioma stem cells by ID4-mediated suppression of miR-9*." (PMID 24358977, 2013). "Id4 also stimulates tumorigenesis in PDGF-induced oligodendroglioma and drives the genesis of glioma-initiating cells via cyclin E and the activation of Notch signaling." (PMID 32708313, 2020). "Platelet-derived growth factor (PDGF) signaling plays a crucial role in inhibitor of differentiation 4 (ID4)-mediated regulation of ECs and Glioma-initiating cells by promoting the PDGF-NOS (nitric oxide synthase)-ID4 signaling axis." (PMID 31600937, 2019). "Moreover, hyperexpression of ID4 was found to be a key regulator of malignant transformation of Ink4a/Arf −/− (cyclin-dependent kinase inhibitor 2A, isoform 4) murine astrocytes in in vivo experiments, resulting in formation of high grade gliomas according to clinical and histological analysis." (PMID 23613880, 2013). "It has also been demonstrated that ID4 protein activates SRY (sex determining region Y)-box 2 (SOX2) transcription in GBM and glioma stem cells." (PMID 23613880, 2013). "One possible explanation is that ID4 up-regulation activates SOX2 through inhibition of a microRNA, mir-9*, which is a direct negative regulator of SOX2, as shown in glioma cell lines." (PMID 23613880, 2013). "The functions of Id4, OLIG1, and OLIG2 during normal development, and our data suggest that Id4 and potentially other proteins such as FABP7 and PTPRZ1 might account for the formation of distinct glioma subtypes during oncogenic progression." (PMID 16018821, 2005). "Based on the function of Id4, OLIG1, and OLIG2 during normal development, our data suggest that Id4 and potentially other genes such as Fabp7 and Ptprz1 might account for the formation of distinct glioma subtypes during oncogenic progression." (PMID 16018821, 2005).